PCA3 (prostate cancer associated 3)
Diseases named in the same sentence as PCA3 in open-access papers (continued):
Sharing a sentence is not in itself a finding about the gene and the disease.
prostate carcinoma (continued). "This is ratified by the results obtained in this paper and others, such as the meta-analysis proposed by Ruiz and Márquez (2010), who evaluated the detection of the PCA3 gene product through antigen detection in urine samples, as a biomarker for prostate cancer." (PMID 31120936, 2019). "PCA3 and TMPRSS2-ERG in combination with the Prostate Cancer Prevention Trial risk calculator may help in deciding the urgency of biopsy after an elevated serum PSA." (PMID 31013716, 2019). "PCA3 detection has been used in urine-based molecular diagnostic test that was approved by the Food and Drug Administration (FDA) in the USA and is now widely applied to prostate cancer detection." (PMID 30466456, 2018). "We detected PCA3, PVT1, and GAS5 lincRNAs as differentially expressed genes in the patient cancer samples compared with adjacent non-tumor tissues; these lincRNAs have been recently shown to be associated with prostate cancer." (PMID 29875794, 2018). "We suspect that, like PSA and PCA3, other prostate cancer biomarkers may be significantly altered by finasteride and should be interpreted cautiously in patients receiving this medication class." (PMID 30300367, 2018). "Also, similar results were obtained after characterizing lncRNAs MALAT1 and PCA3 as biomarkers in prostate cancer patients." (PMID 28634418, 2017). "Also, the measurement of lncRNA PCA3 in patient urine samples has been shown to allow more sensitive and specific diagnosis of prostate cancer than the widely used prostate-specific antigen (PSA) serum levels." (PMID 28634418, 2017). "PCA3 is an FDA-approved assay used to select patients at risk for prostate cancer who need repeat prostate biopsies after a prior negative biopsy." (PMID 28423633, 2017). "It has indicated that the overexpressed PCA3 could modulate prostate cancer cells survival by altering androgen receptor (AR) signaling." (PMID 28915709, 2017). "Prostate Cancer 3 (PCA3) is a long non-coding RNA (ncRNA) upregulated in prostate cancer (PCa)." (PMID 28380027, 2017). "For instance, PCA3 is a prostate specific lncRNA, overexpressed in prostate cancer." (PMID 28631377, 2017). "Detection of PCA3 in urine outperformed PSA in prostate cancer diagnosis." (PMID 28781594, 2017). "The hypothesis is discussed that prostate cancer marker lncRNA PCA3 was introduced into the human genome by an oncogenic virus, and that viral infection‐related mechanisms might underlie its overexpression and prostate cancer initiation and/or progression." (PMID 28751581, 2017). "To determine whether urinary EVs could be used to examine other genes associated with prostate cancer we investigated the differential expression of androgen receptor (AR), BIRC5, ERG, PCA3, TMPRSS2:ERG and TMPRSS2 in Bx Pos versus Bx Neg patients." (PMID 27144529, 2016). "Moreover, several lncRNAs, such as PCA3 and MALAT-1, can be used as diagnostic urinary biomarkers for prostate cancer, thus DANCR expression in the urine of prostate cancer patients should be measured and analyzed in the future." (PMID 27191265, 2016). "This study showed that increased PCA3 in biopsy tissue correlated with prostate cancer and that the PCA3 assay could aid in diagnosis of prostate cancer in a limited number of Chinese men." (PMID 26628213, 2015). "We described the selection of a novel nucleic acid antibody-like prostate cancer (PCa) that specifically binds to the single-stranded DNA molecule from a 277-nt fragment that may have been partially paired and bound to the PCA3 RNA conformational structure." (PMID 26174796, 2015). "Many lncRNAs have been mapped at cancer risk loci in the human genome, such as PTCSC3 (14q13.3) in thyroid cancer, PCA3 (9q21–22) in prostate cancer, ANRIL (9p21) in prostate and breast cancers, leukemia and melanoma, MALAT1 (11q13) in liver, colorectal, prostate, bladder and lung cancers." (PMID 25338714, 2015). "PCA3 has been included in nomograms to predict prostate cancer (PCa) at IBx or repeated Bx." (PMID 26362197, 2015).
prostate carcinoma (continued). "Therefore, PCA3 can be used as a noninvasive urine-based test for large-scale screening protocols and for predicting prostate carcinomas aggressiveness." (PMID 26448935, 2015). "The search was conducted using a free-text protocol that included the following terms: prostate cancer, multiparametric magnetic resonance, clinically insignificant prostate cancer, genetic and/or epigenetic factors, PCA3, active surveillance, and focal therapy." (PMID 27351008, 2014). "Indeed, one lncRNA (PCA3) is already used in the clinical setting as a biomarker for early prostate cancer detection." (PMID 24346158, 2014). "PCA3 is a valuable diagnostic biomarker for prostate cancer, it did not correlate with biopsy Gleason score." (PMID 23759986, 2013). "In spite of this fast clinical translation for PCA3 analysis in prostate cancer, the biological function of PCA3 is unknown." (PMID 23887658, 2013). "One of the most promising biomarkers for prostate cancer is the non-coding RNA PCA3." (PMID 24040105, 2013). "Further studies later indicated that PCA3 is a very specific prostate cancer gene." (PMID 23455466, 2013). "The selected markers are those with increased expression in prostate cancer such as PCA3 and AGR2." (PMID 23029164, 2012). "PCA3 is a non-coding RNA (ncRNA) that is highly expressed in prostate cancer (PCa) cells, but its functional role is unknown." (PMID 23130941, 2012). "The only marker that has been introduced into clinic remains Prostate Cancer Gene 3 (PCA3)." (PMID 24281166, 2010). "Unfortunately, the positivity of the research prototype PCA3 assay used in these experiments was relatively low (less than 30% of androgen-independent prostate cancer specimens), and there were insufficient numbers of patient samples for a clinical correlation." (PMID 20598135, 2010). "The NOS3 transcript levels presented a bimodal behavior in tumor development and may be used as a biomarker together with the PCA3 marker for molecular staging of the prostate cancer." (PMID 18823560, 2008). "PCA3 has a potential for use as a screening test for prostate cancer." (PMID 19675766, 2007). "Importantly, the designed metal-enhanced near-infrared fluorescent satellite structure probe has been successfully used to detect PCA3 in human serum samples and prostate cancer cell lysates, demonstrating promising potential in the field of clinical cancer diagnosis." (PMID 37298846, 2023). "Currently, only one lncRNA, PCA3, has been successfully translated into an FDA-approved molecular diagnostic test, namely, PCA3 ProgensaTM (Gen-Probe Inc., San Diego, CA, USA), which is primarily recommended for patients who have previously had a negative biopsy for prostate cancer." (PMID 37670949, 2023). "PCGEM1 was chosen in addition to PCA3 as it has previously been demonstrated to be a prostate tissue-specific, androgen-regulated non-coding RNA that is functionally involved in the development of prostate cancer and significantly over-expressed in AA men with prostate cancer." (PMID 36768533, 2023). "PCA3 urine assay could therefore be a useful marker in detecting prostate cancer in our population." (PMID 36246565, 2022). "Notably, PCA3 is probably the most important lncRNA biomarker for prostate cancer." (PMID 36497036, 2022). "For example, the lncRNA PCA3, which is often found to be overexpressed in prostate cancer, is already used for clinical diagnostics, as PCA3 is detectable in urine samples from patients with prostate cancer, exemplifying the high potential of lncRNAs as tumor markers." (PMID 32331331, 2020). "Moreover, there are 14 literature evidences reporting upregulated PCA3 in prostate cancer." (PMID 32142370, 2020). "PCA3 might be used as a biomarker for the diagnosis of prostate cancer and PCGEM1 involved in c-MYC activation and androgen receptor transcriptional activation was associated with the progression of prostate cancer." (PMID 31448238, 2019).
prostate carcinoma (continued). "Interestingly, several well-known genes, despite being recommended for their utility in the identification of patients at risk of prostate cancer at RNA expression level, are by far not in the top of this list (e.g. in urine; PCA3, HOXC6, DLX1)." (PMID 31170942, 2019). "Although the current study has found that the polymorphism PCA3 -845 G>A was not correlated with progression to prostate cancer in an Eastern Chinese population, this might have clinical implications on prostate cancer heterogeneity around the World." (PMID 29412547, 2018). "The RNA signatures obtained from our randomly selected first cohort of clinical urine samples were promising in that they could detect cancer in four out of five pre-op specimens based on the six known prostate cancer markers including PCA3, the current urine-based marker." (PMID 23029164, 2012). "This test quantifies the prostate cancer gene 3 (PCA3) and PSA RNA levels in post-DRE first-catch urine specimens to aid in the detection of prostate cancer among men aged 50 years or older with elevated serum PSA and history of negative biopsy results." (PMID 41374944, 2025). "In prostate cancer, ARHGAP21 affects tumor progression by regulating the expression of the PCA3 gene, but its specific role in GC is still unclear." (PMID 40191191, 2025). "ExoDx analyses exosomal RNA of three genes that are elevated in high-grade prostate cancer: ERG, PCA3 and SPDEF." (PMID 40115018, 2025). "In one study, the authors developed a urinary exosomal lncRNA assay incorporating PCA3 and MALAT1 to diagnose prostate cancer and high-grade prostate cancer." (PMID 39859516, 2025). "Such a multifaceted approach, combining mRNA expression analysis of PCA3, PSMA, and AR genes with sPD-L1 levels, provides a comprehensive understanding of prostate cancer’s characteristics." (PMID 39859417, 2025). "Donovan MJ and colleagues, including Sanda MG, demonstrated that identifying exosomal PCA3 in urine and assessing T2:ERG expression levels in urine can aid in the early detection of prostate cancer, as well as monitoring disease progression and recurrence." (PMID 39090720, 2024). "The best-known lncRNAs used for diagnosis of cancer is PCA3 (Prostate Cancer Antigen 3, also known as DD3) for the diagnosis of prostate cancer." (PMID 37143733, 2023). "Expression levels of PCA3 and MALAT1 in urinary exosomes have been shown to be superior to the currently used clinical parameters in detection of prostate cancer, particularly high-grade ones." (PMID 37025585, 2023). "A pilot study showed the presence of two known prostate cancer biomarkers, PCA-3 and TMPRSS2: ERG, in exosomes isolated from patients’ urine as a potential diagnosis and monitoring of prostate cancer patient status." (PMID 37456253, 2023). "PCA3, also known as DD3, is a prostate-specific mRNA biomarker that has promising potential for the detection of prostate cancer (PCa)." (PMID 37958246, 2023). "In prostate cancer cells, ADAR1 mediates the formation of prune homolog 2 with BCH domain (PRUNE2)/prostate cancer antigen 3 (PCA3) double-stranded RNA by regulating PRUNE2 and PCA3 levels via adenosine-to-inosine RNA editing." (PMID 37524814, 2023). "Possibly the best studied example is prostate cancer antigen 3 (PCA3), an intronic lncRNA antisense to PRUNE2 a tumor suppressor gene whose downregulation promotes the development of prostate cancer." (PMID 35865634, 2022). "The urine-exosome signature is derived from genes known to play a role in prostate cancer initiation and progression, including ERG, PCA3, and SPDEF." (PMID 34593984, 2022). "Utilizing the expression levels from three genes (i.e., PCA3, ERG, and SPDEF), EPI provides a risk score predicting whether a patient presenting for their first biopsy with an equivocal PSA from 2 to 10 ng/mL is likely to have GG2 or greater (high-grade) prostate cancer." (PMID 34593984, 2022).
prostate carcinoma (continued). "For example, PCA3, PCGEM1, and PRNCR1 are highly expressed in prostate cancer, while differential HULU expression is related to liver cancer and liver metastasis." (PMID 36389111, 2022). "Prostate cancer specific biomarker PSMA and PCA3 expression was also detected from the cellular material extracted from the inner channel." (PMID 34095091, 2021). "PCA3 and PSMA are overexpressed in prostate cancer; thus, they were used as PCa-specific biomarkers in our test." (PMID 34771706, 2021). "These strategies based on CTC detection are complementary to those involving the determination of prostate cancer biomarkers such as prostate-specific antigen (PSA) and prostate cancer antigen 3 (PCA3)." (PMID 32604896, 2020). "Although its biological function is unclear, a urinary PCA3 detection kit was developed and approved by the US Food and Drug Administration (FDA) for prostate cancer diagnosis." (PMID 31653018, 2019). "Many prostate cancer molecular biomarkers have been identified; however, only a few are Food and Drug Administration (FDA) approved (PSA in 1994, phi in 2012, and PCA3 in 2012)." (PMID 31013716, 2019). "Further, in combination with serum PSA (cut-off of 10 ng/mL) and urinary PCA3, T2-ERG provides an improved accuracy in diagnosing prostate cancer with a sensitivity and specificity of 80% and 90%, respectively." (PMID 31013716, 2019). "It was found that the lncRNA PCA3 in urine has a higher specificity and sensitivity than serum PSA in prostate cancer patients." (PMID 27906682, 2017). "The search of lncRNA biomarkers in PCa is exemplified by PCA3, a well characterized lncRNA that has been approved by the FDA for clinical decisions about repeat biopsy of prostate cancer." (PMID 28272371, 2017). "Nilsson was able to detect two known prostate cancer biomarkers, PCA3 and TMPRSS2-ERG, in exosomes isolated from urine of prostate cancer patients, first showing their potential for prostate cancer diagnostics." (PMID 27305142, 2016). "The use of EVs was also examined as a potential platform to non-invasively differentiate Bx Pos versus Bx Neg patients via the detection of known prostate cancer genes TMPRSS2:ERG, BIRC5, ERG, PCA3 and TMPRSS2." (PMID 27144529, 2016). "The most prominent example of lncRNAs application in routine clinical practice is PCA3, a FDA-approved biomarker for prostate cancer." (PMID 26064090, 2015). "One of the most elucidative examples of this approach is the analysis of circulating PCA3 lncRNA and Prostate-Specific Antigen (PSA) protein for prostate cancer diagnosis." (PMID 26516918, 2015). "The established methods for detecting prostate cancer (CaP) are based on tests using PSA (blood), PCA3 (urine), and AMACR (tissue) as biomarkers in patient samples." (PMID 25889691, 2015). "Recently, the potential prostate cancer biomarkers, such as prostate cancer antigen 3 (PCA3), TMPRSS2-ERG gene fusions and p501s (prostein), were investigated as auxiliary diagnosis candidates for prostate cancer." (PMID 24571686, 2014). "Extensive research efforts have suggested a number of candidate biomarkers and biomarker panels, including PCA3, TMPRSS-ERG, Ki-67, and CCP score to improve the clinical management of prostate cancer." (PMID 25193387, 2014). "We have previously shown that the prostate cancer cell line LNCaP expresses high levels of both BMCC1-1 and PCA3 RNAs." (PMID 24040105, 2013). "Thus, the PCA3 marker may be informative to identify prostate cancer in the Bx(+)/Fx(−) subgroup." (PMID 24133629, 2013). "RNA from a dilution series of prostate cancer lines C4-2 and PC3 was prepared, and hybridized to a probe library of six selected genes: KLK3, CD90/THY1, AGR2, HPN, PCA3, UPK3A." (PMID 23029164, 2012). "The noncoding RNA PCA3, which was initially characterized as Differential Display Code 3 (DD3), is prostate-tissue-specific and highly overexpressed in more than 95% of primary prostate cancers." (PMID 23130941, 2012).
prostate carcinoma (continued). "CTCs were successfully enriched and detected in men with advanced prostate cancer using an immunomagnetic enrichment procedure coupled with amplified molecular assays for PSA, PCA3, and TMPRSS2:ERG gene fusion mRNAs." (PMID 20598135, 2010). "al. reported that addition of PCA3 to a model including prostate volume, DRE result and PSA improved the discrimination of prostate cancer on biopsy from and AUC of 0.67 to 0.75." (PMID 21092177, 2010). "Our objective is to present recent findings on the application of PCA3 and TMPRSS2:ERG in prostate cancer diagnosis and management." (PMID 24281166, 2010). "Comparison of PSA, PCA3 and TMPRSS2:ERG mRNA copy levels in CTC enriched fractions from androgen-independent prostate cancer patients." (PMID 20598135, 2010). "Comparison of PSA, PCA3 and TMPRSS2:ERG mRNA copy levels in CTC enriched fractions from androgen-dependent prostate cancer patients." (PMID 20598135, 2010). "Most of these genes are prostate cancer-related genes (i.e., ERG, PCA3, and AR-V7)." (PMID 39859516, 2025). "The important fact is that PCA3 seems to be more specific for prostate cancer and not elevated due to benign prostatic hyperplasia (BPH)—unlike prostate-specific antigen (PSA) or other non-cancerous conditions." (PMID 41374944, 2025). "Urinary assays like PCA3 detect overexpression of the prostate cancer gene 3, a non-coding RNA highly specific for prostate cancer, and are primarily used after a negative biopsy." (PMID 40868988, 2025). "ExoDx analyzes exosomal RNA (ERG, PCA3, SPDEF) in urine without requiring a digital rectal exam and provides a risk score for high-grade prostate cancer." (PMID 40868988, 2025). "In a novel development, the PCA3 prostate cancer gene, PCAT-1, MALAT-1 PCGEM, and several other long non-coding RNAs were investigated for potential deregulation in PC." (PMID 38723038, 2024). "PRUNE2 is a tumor suppressor gene of particular significance shown in prostate cancer, where its expression is regulated by prostate cancer antigen 3 (PCA3), a non-protein coding gene located on the opposite DNA strand in an intron of PRUNE2." (PMID 36900197, 2023). "Only three studies considered prostate cancer screening programmes, none of which were based purely on PSA testing; one looked at the cost of using prostate cancer antigen 3 (PCA3) urine testing, and the other two considered risk scoring approaches." (PMID 37296430, 2023). "The commercial available assay ExoDx Prostate (IntelliScore) (NCT03235687, NCT03031418, NCT04720599, NCT02702856) is based on the detection of three RNAs (PCA3, SPDEF, ERG) in urinary sEVs from prostate cancer patients by quantitative reverse transcription-polymerase chain reaction (RT-PCR)." (PMID 36242076, 2022). "Thus, we evaluated the diagnostic and prognostic potential of urinary prostate cancer gene 3 (PCA3) as a biomarker for diagnosing prostate cancer and compared the performance characteristics of serum PSA and urinary prostate cancer gene 3 (PCA3)." (PMID 36246565, 2022). "PCA3 as a stand-alone and in combination with DRE could be a suitable complimentary marker in diagnosis and management of prostate cancer." (PMID 36246565, 2022). "The PCA3-Cre-PSEBC-ITSTA system, which is based on combinational activation of two prostate cancer gene promoters, has the ability to study dynamic and quantitative antiandrogen single-cell response from urine and primary cancer tissues harvested from PCa patients." (PMID 34976196, 2022). "Apatient-specific individual risk score is evaluated based on an original algorithm thatcombines the expression level of three RNAs (PCA3 noncoding RNA, ERG mRNA, and SPDEFmRNA), which are correlated with clinically significant prostate cancer, detected directlyin urinary EV RNAs." (PMID 39703905, 2021). "Several other biomarkers for prostate cancer are known, including PCA3, a long non-coded RNA transcript expressed in the urine of prostate cancer patients, which appears to be an ideal biomarker of PCa." (PMID 34884504, 2021).